TAS2R1 (taste 2 receptor member 1)
Description:
Receptor that may play a role in the perception of bitterness and is gustducin-linked. May play a role in sensing the chemical composition of the gastrointestinal content. The activity of this receptor may stimulate alpha gustducin, mediate PLC-beta-2 activation and lead to the gating of TRPM5.
Synonyms: T2R1; TRB7
Tractability: Antibody: its Gene Ontology location is reachable by antibodies, with high confidence; UniProt predicts a signal peptide or a membrane-spanning region. PROTAC: a small molecule that binds it is known.
Target class: Membrane receptor; Taste receptor (taste family GPCR); Taste family G protein-coupled receptor
Gene: Protein-coding gene on chromosome 5 (9,627,347 to 9,712,378, reverse strand). Ensembl gene ENSG00000169777.
Subcellular location: Membrane
Pathways (Reactome):
Signal Transduction: Class C/3 (Metabotropic glutamate/pheromone receptors); G alpha (i) signalling events
Sensory Perception: Sensory perception of sweet, bitter, and umami (glutamate) taste
Gene Ontology:
Molecular function: bitter taste receptor activity; taste receptor activity; G protein-coupled receptor activity
Biological process: detection of chemical stimulus involved in sensory perception of bitter taste; G protein-coupled receptor signaling pathway; sensory perception of taste
Cellular component: membrane; plasma membrane
Genetic constraint (gnomAD): Loss-of-function variants: 0 observed, 0.54 expected, observed/expected ratio (o/e) 0, 90% interval 0 to 1.83. That is too few expected variants to judge how well the gene tolerates losing a copy. Missense variants: 370 observed, 368.69 expected, observed/expected ratio (o/e) 1, 90% interval 0.92 to 1.09. Synonymous variants: 141 observed, 140.67 expected, observed/expected ratio (o/e) 1, 90% interval 0.87 to 1.15.
Homologues: Orthologues: chimpanzee TAS2R1 (93% identical), macaque TAS2R1 (87% identical), dog TAS2R1 (57% identical), pig TAS2R1 (54% identical), rabbit TAS2R1 (54% identical), mouse Tas2r119 (51% identical), rat Tas2r119 (51% identical), tropical clawed frog tas2r7 (29% identical), tropical clawed frog tas2r4 (28% identical), tropical clawed frog t2r10 (27% identical), tropical clawed frog t2r2 (27% identical), tropical clawed frog t2r8 (25% identical), and 9 more. Paralogues in human: TAS2R3 (33% identical), TAS2R9 (30% identical), TAS2R7 (30% identical), TAS2R43 (29% identical), TAS2R46 (29% identical), TAS2R30 (29% identical), TAS2R40 (29% identical), TAS2R41 (28% identical), TAS2R10 (28% identical), TAS2R8 (28% identical), TAS2R14 (28% identical), TAS2R31 (28% identical), and 11 more.
Diseases named in the same sentence as TAS2R1 in open-access papers:
TAS2R1 is named in the same sentence as 11 diseases in open-access papers, as found by Europe PMC text mining. Sharing a sentence is not in itself a finding about the gene and the disease. The quoted sentences say what the papers report.
chronic airway obstruction (1 paper, 2025). "On the other hand, rs2234235 (G) in TAS2R1, identified in this study as a risk allele for nucleocapsid antibody response, was linked to a decreased risk of chronic airway obstruction in the UK Biobank data (p = 0.01; effect size: −0.097)." (PMID 41153757, 2025).
colon cancer (1 paper, 2024). "Differential expression analysis results revealed that compared to normal colon tissue, colon cancer samples exhibited elevated expression levels of TAS2R1, TAS2R4, TAS2R5, TAS2R14, TAS2R19, TAS2R20, and TAS2R38 (p < 0.05), with the exception of TAS2R60, which was downregulated." (PMID 38999959, 2024).
COVID-19 (1 paper, 2025). A disease caused by infection with severe acute respiratory syndrome coronavirus 2. "Additionally, two alleles in TAS2R1 and TAS2R5 were associated with the presence of nucleocapsid antibody, and two alleles in TAS2R1 and TAS2R62P were linked to lower odds of spike antibody seroconversion following COVID-19 vaccination or infection." (PMID 41153757, 2025).
diabetes (1 paper, 2025). "The rs2234235 in TAS2R1 was linked to confirmed/probable infection in individuals with respiratory disease (OR: 2.65; CI: 1.08, 5.61; p = 0.018) or IMID (OR: 7.39; 95% CI: 1.36, 33.8; p = 0.012), as well as in those without diabetes (OR: 2.08; CI: 1.11, 3.57; p = 0.013)." (PMID 41153757, 2025).
ovarian carcinoma (1 paper, 2021). A malignant neoplasm originating from the surface ovarian epithelium. "In more detail, the downregulated gene expression of TAS2R1, 4, 10, and 14 varied in ovarian cancer cell lines of different histotypes and ovarian cystadenocarcinoma tissue in comparison to tissue samples from which these cancer cells are supposed to originate." (PMID 34885005, 2021).
infection (1 paper, 2025). The state of being infected such as from the introduction of a foreign agent such as serum, vaccine, antigenic substance or organism. "In a subgroup analysis, the rs2234235(G) variant in TAS2R1 was associated with a decreased anti-spike response to infection or vaccination in individuals with IMIDs or respiratory disease and an increased risk of SARS-CoV-2 infection." (PMID 41153757, 2025).
TAS2R1 also shares sentences with these, for which no sentence is quoted: autism (1 paper); breast carcinoma (1); cancer (1); ovarian cystadenocarcinoma (1); respiratory disease (1).